MMP9 (matrix metallopeptidase 9)
Diseases named in the same sentence as MMP9 in open-access papers (continued):
Sharing a sentence is not in itself a finding about the gene and the disease.
asthma (continued). "PTGS2, IL10, CTSB, JAK2, and MTOR were significantly downregulated in alveolar lavage fluid with increasing asthma severity, while MMP9, GSK3B, BCL2, EGFR, and CCND1 were upregulated." (PMID 40160461, 2025). "Supporting this finding, a recent study demonstrated that in asthma patients, this integrin subunit is predominantly released by metalloproteinase‐9 (MMP‐9) during asthma exacerbations, as this is when MMP‐9 levels and activity increase." (PMID 39887589, 2025). "MMP-9 (gelatinase B) is typically present at low levels in healthy lungs but is markedly elevated in various lung diseases, including asthma, PF, and COPD." (PMID 39940873, 2025). "Compared to the control, the expression of Mmp9 was significantly increased in both the asthma group and postnatal PAH-exposed group." (PMID 41150507, 2025). "ORMDL sphingolipid biosynthesis regulator 3 promoted angiogenesis through upregulating vascular endothelial growth factor and MMP9 in asthma airway remodeling." (PMID 41150507, 2025). "Elevated levels of MMP-1, MMP-2, MMP-8, and MMP-9 have also been found in the sputum and bronchoalveolar lavage fluid of patients with asthma and COPD." (PMID 40940719, 2025). "The MMP-9 levels negatively correlated with Corynebacterium, which was downregulated in the asthma patients." (PMID 40871265, 2025). "In asthma DEHP, DIBP were strongly associated with MMP9,and in COPD DEHP, DEP, DIBP were associated with MMP9." (PMID 40160461, 2025). "The expression of HSPA1A, PIK3CG and PIK3R6 in the same 10 and 4 pathways was then verified, while the expression of MAPK13 and MMP9 related to severe asthma was also confirmed." (PMID 39088141, 2024). "Among the genes involved in these important signaling pathways, HSPA1A, PIK3CG and PIK3R6 seemed to be associated with moderate asthma, while MAPK13 and MMP9 appeared to be associated with severe asthma." (PMID 39088141, 2024). "In severe asthma, which was dominated by neutrophils, the process of MMP-9 was found to be upregulated." (PMID 39088141, 2024). "Our results also indicated that SRT polyphenols significantly inhibited the elevated expression of α-SMA and MMP9, underscoring their potential to effectively alleviate inflammatory responses, which is crucial for therapeutic efficacy in asthma treatment." (PMID 39796021, 2024). "Among MMP family members, matrix metalloproteinase MMP9 is enriched in lungs of asthma, IPF and COPD, and also promotes lung remodeling." (PMID 38166679, 2024). "The increased expression of MMP-9 was found to be associated with collagen III, collagen V, and tenascin deposition in the basement membrane of asthma individuals." (PMID 38562155, 2024). "Elevated concentrations of exhaled MMP-9 were identified in individuals with severe asthma when compared to those with mild to moderate." (PMID 38562155, 2024). "Overall, this study discovered a total of five genes, including HSPA1A, PIK3CG, PIK3R6, MAPK 13 and MMP9, as potential biomarkers of moderate or severe asthma." (PMID 39088141, 2024). "MMP-9, which is present in low quantities in healthy lungs, is abundant in lung diseases characterized by tissue remodelling, such as asthma, pulmonary fibrosis, and chronic obstructive pulmonary disease (COPD)." (PMID 37509076, 2023). "Airway inflammatory diseases are characterized by airway remodeling and inflammatory responses, and MMP-9 mediates inflammatory respiratory diseases, including asthma and COPD." (PMID 37571300, 2023). "Several studies reported that NGAL and MMP-9 levels were increased in the bronchoalveolar lavage samples of patients with asthma as a result of structural alterations in the airways." (PMID 35707392, 2022). "In this study, we found that plasma concentrations of MMP-9 are increased in asthma patients compared to controls." (PMID 34342773, 2022). "In a murine model of asthma, MMP-9 knockout mice exhibited a reduced level of immune cell infiltration as well as decreased bronchial hyperresponsiveness compared to wild-type mice." (PMID 36359917, 2022).
asthma (continued). "Elevated secretion of MMP-9 was detected in patients with asthma, acute respiratory distress syndrome (ARDS), and chronic obstructive pulmonary disease (COPD)." (PMID 35892136, 2022). "Circulating PMNs from aspirin-exacerbated asthma patients displayed increased ROS production, CD11b expression and CXCL8 and MMP-9 release compared to aspirin-tolerant asthma patients." (PMID 34342773, 2022). "Fourteen core targets including IL4, IFNG, and MMP9 were identified for the treatment of asthma by SYD." (PMID 36212941, 2022). "The maximal % inhibition in neutrophils from severe asthma patients was 45.1 ± 7.5% and 63.44 ± 2.44 for IL-8 and MMP9 release, significantly lower than in neutrophils from healthy and COPD patients." (PMID 35332239, 2022). "IL-1β, IL-6, and MMP-9, which are regulated by the NF-κB pathway, are major mediators of airway inflammation and remodeling in asthma." (PMID 36313381, 2022). "Various studies have demonstrated that MMP-9 plays a major role in the onset and exacerbation of asthma." (PMID 35631208, 2022). "MMP-9, present within tertiary granules of neutrophils, has been detected in the bronchoalveolar lavage (BAL) of patients with asthma and is associated with neutrophil counts." (PMID 36359917, 2022). "TIMP-1 antagonizes MMP-9 activity, and a lower MMP-9/TIMP-1 ratio in sputum from untreated stable asthmatics suggests an overproduction of TIMP-1 over MMP-9 in patients with stable asthma." (PMID 33628848, 2021). "The elevated levels of MMP-9 in asthmatic airways make MMP-9 a likely pathological angiogenic player in asthma as well." (PMID 33628848, 2021). "Another research showed that higher levels of IL-6 and MMP-9 were observed in asthma patients compared to the control group and in severe asthma as compared to moderate asthma." (PMID 34221070, 2021). "Compared to the control mice, mice with OVA-induced asthma showed a significantly higher expression of MMP-9 protein around the small airways (P < 0.05)." (PMID 34526979, 2021). "Sin also inhibited MMP7, MMP9, and vimentin expression in 16HBE cells and respiratory epithelial cells from mice with asthma." (PMID 34804018, 2021). "MMP-9 also participated in asthma-related epithelial structural remodeling and functional damage by changing the immune localization of tight junction." (PMID 33740985, 2021). "In this study, administration of YTE decreased the expression levels of MMP-9 in mice with asthma, as well as reducing ERK phosphorylation." (PMID 34055011, 2021). "A recent study using a treatment with omalizumab, an anti-IgE monoclonal antibody, demonstrated that a decrease in BALF levels of MMP9 correlates with a lower asthma exacerbation rate in SA patients." (PMID 35387021, 2021). "ERK is a mitogen-activated protein kinase MAPK and is regarded as a critical factor in inflammatory responses; its phosphorylation markedly increases the expression levels of MMP-9 during the progression of asthma." (PMID 34055011, 2021). "In the follow-up study, the ethanol extract and (E)-4-(3′,4′-dimethoxyphenyl)but-3-en-1-ol from Z. cassumunar inhibited pro-MMP-9 cleavage by MMP-9 in asthma induced by house dust mite allergens." (PMID 33921835, 2021). "In this study, we demonstrated that CRE treatment resulted in a reduction in MMP-9 expression with the reduction in phosphorylation of NF-κB in animals with asthma." (PMID 34679759, 2021). "Aligned with this, a dysregulated balance of the MMP9/TIMP1 ratio in sputum has been shown to associate with airway remodeling and asthma exacerbation." (PMID 35387021, 2021). "Neutrophils, matrix metallopeptidase 9 (MMP-9) and IL-6 have all been proposed as potential candidates, but none have been shown to represent all phenotypic subgroups of the Th2-low asthma endotype." (PMID 33926084, 2021). "The Western blotting results also showed that Sin obviously suppressed the expressions of MMP7 and MMP9 in the lungs of the mice with asthma." (PMID 34804018, 2021).
asthma (continued). "MMP-9 is a 92 kDa gelatinase that participates in ALI/ARDS in patients with asthma, pulmonary fibrosis, and chronic obstructive pulmonary disease." (PMID 33800947, 2021). "Matrix metalloproteinase 9 (MMP-9), an important enzyme regulating the synthesis and degradation of ECM, is associated with airway remodeling and lung injury in asthma and COPD." (PMID 32829707, 2020). "Previously, the role of MMP-9 has been implicated in various cellular processes such as cellular migration and airway inflammatory responses in COPD and Asthma." (PMID 33198714, 2020). "In the present study, we found a link (involving IL-17A, MMP-1, and MMP-9 expression) between cigarette smoke and neo-osteogenesis in AE with asthma and CRS." (PMID 31653934, 2019). "The high positive correlations of MMPs and neutrophil percentages in BALF suggest these cells to be the origin of MMPs, in particular MMP-9, in equine asthma with neutrophils being one of the most important sources of MMPs." (PMID 31316303, 2019). "One is that the elevated MMP-9 level is not only observed in asthma, but also existed in others inflammatory disease, such as acute respiratory tract diseases and chronic obstructive pulmonary disease (COPD)." (PMID 30931075, 2019). "AMs of asthma with a fast FEV1 decline released a higher level of MMP-9 (8.52 ± 3.53 pg/mL, p < 0.05) than those of a slow FEV1 decline (0.99 ± 0.20 pg/mL)." (PMID 31547356, 2019). "Nevertheless, a defensive function of MMP-9 in asthma was reported through a heightened inflammation in MMP9-deficient mice." (PMID 31547356, 2019). "The ratio of MMP-9 to its natural inhibitor (TIMP-1) in bronchoalveolar lavage (BAL) fluid was also higher in children with symptomatic asthma, as compared to that of healthy controls." (PMID 30931075, 2019). "More importantly, 11 mRNAs were overlapped in our sequencing data, MalaCards database and asthma-associated genes, including IL4, IL-10, MMP9, VCAM-1, Il1rl1, Alox5, Il1rn, Ccr3, Cysltr1, Epx, and Ccl24." (PMID 31231429, 2019). "MMP-1 and MMP-9 expression was increased in the nasal tissues of smokers with asthma and CRS via real-time PCR and western blot." (PMID 31653934, 2019). "In a recent study, unregulated levels of connective tissue growth factor (CTGF) correlated with the MMP-9 level were found in the airway remodeling of asthma." (PMID 31284537, 2019). "The level of MMP-9 was significantly higher in asthma with a slow FEV1 decline compared to normal subjects." (PMID 31547356, 2019). "The third study assessed the cytokines tumor necrosis factor (TNF) and IL-8, and a marker of airway remodeling [matrix metalloproteinase (MMP)-9] in EBC in a very small group (n = 4) of children with an asthma exacerbation." (PMID 31106182, 2019). "Metalloproteinase expression, especially MMP-9, seems to play an important role in the asthma remodeling process." (PMID 30364003, 2018). "Evaluation of inflammatory markers interleukin-6 (IL-6) and matrix metalloproteinase-9 (MMP-9) in serum showed higher levels in asthmatic patients vs controls and were associated with a more severe asthma." (PMID 30598830, 2018). "Patients with severe asthma are reported to have increased levels and activity of MMP-9 in their sputum compared with mild asthmatics and normal subjects." (PMID 30068332, 2018). "MMP-9 exhibits elastinolytic and gelatinolytic activities and its levels in the lung have been shown to correlate with asthma severity as well as with the degree of subepithelial fibrosis in patients suffering from asthma." (PMID 28190087, 2017). "Anti-MMP-9 therapy has been shown to be useful for preventing airway inflammation and remodeling in murine model of asthma." (PMID 26783416, 2016). "MMP-9 on the other hand shows very low levels in health, but increases dramatically during exacerbations of asthma and RAO as well as in idiopathic pulmonary fibrosis." (PMID 27938355, 2016).
asthma (continued). "The present study demonstrates that empirical prescriptions of TCM can effectively control asthma attacks and reduce the levels of IL-10, IL-17, and MMP-9 in peripheral blood." (PMID 27378824, 2016). "Elastinolytic and collagenolytic activity was found in several studies on human asthma, in particular increased levels of MMP-9, but also MMP-2." (PMID 27938355, 2016). "While reviewing studies conducted so far, elevated MMP-9 was found in blood, sputum and bronchoalveolar lavage from patients with asthma exacerbation." (PMID 26123447, 2016). "MMP9 subdues AHR in asthma models but little is known about the impact of elevated concentrations of MMP9 on AHR during RSV infection." (PMID 26284919, 2015). "Recent studies have implicated MMP-9 dysregulation to be associated with several lung disorders, such as chronic obstructive lung disease (COPD), ALI, asthma and chronic lung disease of prematurity." (PMID 26264019, 2015). "MMP-9 is a downstream target of IL-33,16 and activity is increased in sputum from patients with severe asthma who are unresponsive to steroid therapy." (PMID 25746970, 2015). "Recently, neovastat (AE-941), natural MMP-9 antagonist, has been shown to display some beneficial properties in murine model of asthma." (PMID 25650123, 2015). "This assumption was developed from the observation that increased MMP-9/EBC activity in our asthma group significantly correlated with high levels of total IgE." (PMID 25650123, 2015). "It strongly supports the need for further research focused on implementation of modulators of MMP-9 activity also in asthma treatment." (PMID 25650123, 2015). "By the fact that insulin infusion suppresses the expression of IL-4, ADAM-33, LIGHT, and LTBR and the plasma concentrations of NOM and MMP-9, the efficacy of insulin in the treatment of asthma needs to be assessed." (PMID 25642424, 2015). "The MMP9 levels observed to kill RSV are within the range frequently observed in RSV infections in infants and during RSV-associated asthma exacerbations." (PMID 26284919, 2015). "Our study has shown for the first time that children with stable asthma, when compared to healthy controls, had significantly elevated active form of MMP-9 in their EBC." (PMID 25650123, 2015). "The mean concentrations of MMP-9 in breath condensates of patients in asthma group were statistically significantly higher than in healthy controls." (PMID 25650123, 2015). "For that reason, an actual in vivo activity of MMP-9 in EBC of asthma-suffering individuals still needs to be determined." (PMID 25650123, 2015). "Despite chronic treatment with inhaled steroids mean MMP-9/EBC activity in asthma group was significantly higher than in healthy controls." (PMID 25650123, 2015). "In a mouse model, TLR2 activation of neutrophils led to the release of MMP9, which was protective against experimentally-induced asthma." (PMID 24983946, 2014). "A number of studies have demonstrated the presence of increased levels of MMP9 in the serum and sputum of patients with classic asthma." (PMID 25187823, 2014). "Patients with classic asthma have elevated levels of MMP9 in their serum, sputum and bronchoalveolar lavage fluid (BALF)." (PMID 25187823, 2014). "An elevated circulation level of MMP-9 is also found in patients suffering from asthma exacerbation." (PMID 24782592, 2014). "Previous studies have revealed the role of matrix metalloproteinase 9 (MMP9) in asthma and chronic obstructive pulmonary disease (COPD)." (PMID 25187823, 2014). "A constitutive low intensity expression of MMP-9 was found in both healthy controls and patients with asthma." (PMID 24950767, 2014). "Our study showed LXR agonist reduced the high levels of TGF-β1 and MMP-9 in the murine model of asthma." (PMID 24681543, 2014). "There is an increasing evidence that inflammatory proteins, such as VCAM-1, ICAM-1, cPLA2, COX-2, and MMP-9 are involved in the pathogenesis of respiratory diseases, such as asthma and COPD." (PMID 23690670, 2013).
asthma (continued). "Patients with asthma have an increased gelatinolytic activity linked to MMP-2 and MMP-9 and higher levels of tissue inhibitor of metalloproteinase-1 (TIMP-1; a natural inhibitor of MMPs) in their sputum." (PMID 23690670, 2013). "The levels of MMP-9 in sputum or in plasma have been related to the severity of asthma, with more severe asthmatics having higher levels than those with mild asthma." (PMID 24073339, 2013). "Previous studies have shown that in several diseases, including cystic fibrosis and asthma, patients have increased expression of MMP-9 in the lungs as well as decreased levels of intact SP-D." (PMID 22860023, 2012). "Another important aspect of asthma is that the matrix metalloproteinase-9 (MMP-9) level increases significantly in the bronchoalveolar lavage fluid (BALF), blood, and sputum of people with asthma." (PMID 23244755, 2012). "Increased levels of MMP-1, MMP-2, and MMP-9 have been reported in the sputum and lung parenchyma of asthma or COPD patients." (PMID 23226927, 2012). "MMP-9 is a protease with a wide variety of substrates, and has been found to be dysregulated in a myriad of lung diseases ranging from asthma to cystic fibrosis; in many of these conditions, there are decreased levels of SP-D." (PMID 22860023, 2012). "It is quite possible that the active cleavage of SP-D will render a novel mechanism for the pathogenesis in diseases like asthma, emphysema, and allergies, in which MMP-9 is over-expressed." (PMID 22860023, 2012). "In contrast, bencycloquidium bromide, a selective M3 receptor antagonist, inhibited ovalbumin-induced expression of MMP-9 mRNA in a murine asthma model, indicating that M1 and M3 receptors mediate profibrotic and inflammatory response via specific MMPs." (PMID 23226927, 2012). "Specifically, of interest with regards to lung disease are the findings that MMP9 concentrations were reduced in sputum from a group of patients with refractory asthma that were receiving clarithromycin." (PMID 19503797, 2009). "A correlation between fibrosis in asthma and MMP-9 expression has recently been demonstrated in a mouse model of chronic asthma." (PMID 19857272, 2009). "It has previously been shown that Mmp2 and Mmp9 are critically required by DC for recruitment to the airways in a murine model of asthma and for the migration of DC from the skin to lymph nodes." (PMID 19149869, 2009). "MMP-9 has been thought to be particularly important in the pathogenesis of inflammatory lung diseases, including acute lung injury, asthma, and COPD." (PMID 18007984, 2007). "Neutrophils potentially contribute to airway gland hypersecretion, bronchial hyper-reactivity and to airway wall remodelling by producing matrix metalloproteinase-9 (MMP-9) observed in broncho-alveolar lavage fluid from moderate-to-severe asthma patients." (PMID 17083726, 2006). "Among them, MMP‐9 is capable of degrading components of the cellular matrix and contributes to tissue remodeling in adult respiratory disease, and its production varies depending on asthma phenotype." (PMID 40952045, 2026). "Furthermore, it provides novel insights by linking PAH-induced epigenetic changes of MMP9—a key gene in extracellular matrix remodeling—to the pathogenesis of asthma." (PMID 41150507, 2025). "Matrix metalloproteinase 9 (MMP9), as a disease marker in COPD has been supported by evidence,Its upregulation has also been shown to be associated with the degree of asthma inflammation." (PMID 40160461, 2025). "Furthermore, oral administration of Lactobacillus GG (LGG) alleviates asthma by reducing the expression levels of alveolar lavage fluid and serum matrix metalloproteinase-9 (MMP-9), thereby inhibiting inflammatory cell infiltration in the lungs." (PMID 41562083, 2025). "Taken together, the process of the airway may initiate with an excess of TGF-β1 and MMP-9, often derived from the inflammatory processes occurring in both obesity and asthma." (PMID 38562155, 2024).